ENSG00000212395
Gene: Small nucleolar RNA gene on chromosome 9 (131,782,860 to 131,782,958, reverse strand). Ensembl gene ENSG00000212395.
Gene Ontology:
Biological process: RNA processing
Cellular component: nucleolus
Homologues: Paralogues in human: SNORA67 (70% identical).